KCNK15 (potassium two pore domain channel subfamily K member 15)
Description:
Probable potassium channel subunit. No channel activity observed in heterologous systems. May need to associate with another protein to form a functional channel.
Synonyms: TASK5; K2p15.1; dJ781B1.1; KT3.3; KIAA0237; TASK-5; KCNK11; KCNK14
Tractability: Small molecule: it belongs to a druggable protein family. Antibody: its Gene Ontology location is reachable by antibodies, with high confidence; UniProt predicts a signal peptide or a membrane-spanning region.
Gene: Protein-coding gene on chromosome 20 (44,745,865 to 44,752,313, forward strand). Ensembl gene ENSG00000124249.
Subcellular location: Membrane
Pathways (Reactome):
Muscle contraction: Phase 4 - resting membrane potential
Gene Ontology:
Molecular function: voltage-gated monoatomic ion channel activity; potassium ion leak channel activity; potassium channel activity
Biological process: cellular response to acidic pH; potassium ion transmembrane transport
Cellular component: plasma membrane; membrane
Genetic constraint (gnomAD): Loss-of-function variants: 9 observed, 5.08 expected, observed/expected ratio (o/e) 1.77, 90% interval 0.96 to 1.96. That is too few expected variants to judge how well the gene tolerates losing a copy. Missense variants: 467 observed, 386.2 expected, observed/expected ratio (o/e) 1.21, 90% interval 1.12 to 1.3. Synonymous variants: 224 observed, 192.99 expected, observed/expected ratio (o/e) 1.16, 90% interval 1.04 to 1.3.
Homologues: Orthologues: chimpanzee KCNK15 (96% identical), dog KCNK15 (83% identical), pig KCNK15 (78% identical), rabbit KCNK15 (77% identical), guinea pig KCNK15 (77% identical), rat Kcnk15 (75% identical), mouse Kcnk15 (74% identical), tropical clawed frog kcnk15 (61% identical), zebrafish kcnk15 (58% identical), Drosophila melanogaster Task6 (42% identical), Drosophila melanogaster Task7 (38% identical), Caenorhabditis elegans twk-26 (25% identical), and 9 more. Paralogues in human: KCNK9 (56% identical), KCNK3 (53% identical), KCNK12 (27% identical), KCNK5 (27% identical), KCNK16 (26% identical), KCNK1 (25% identical), KCNK10 (25% identical), KCNK2 (25% identical), KCNK4 (25% identical), KCNK6 (24% identical), KCNK13 (24% identical), KCNK17 (24% identical), and 2 more.
Diseases named in the same sentence as KCNK15 in open-access papers:
KCNK15 is named in the same sentence as 17 diseases in open-access papers, as found by Europe PMC text mining. Sharing a sentence is not in itself a finding about the gene and the disease. The quoted sentences say what the papers report.
breast carcinoma (3 papers, 2021 to 2025). "The role of KCNK6 in cancer is not well understood, but under-expression of KCNK6 and KCNK15 was associated with the triple-negative subtype of breast cancer." (PMID 34281234, 2021). "The RNA expression level of KCNK2, KCNK5, KCNK9, KCNK13, and KCNK15 were validated in human breast cancer cell lines." (PMID 35656548, 2022). "We found that KCNK2 and KCNK5 was downregulated in breast cancer, while KCNK9, KCNK13, and KCNK15 was upregulated in breast cancer." (PMID 35656548, 2022). "Overexpression of KCNK5, KCNK9, and KCNK12, as well as reduced expression of KCNK6 and KCNK15, was significantly correlated with triple-negative subtype in breast carcinoma." (PMID 35656548, 2022). "Our results revealed that KCNK9, KCNK13, and KCNK15 was significantly upregulated in breast cancer cell lines including MDA-MB-231 and SK-BR-3 cell lines, while KCNK2 and KCNK5 was downregulated in breast cancer cell lines comparing with breast epithelial cell line MCF-10A." (PMID 35656548, 2022). "Breast cancer studies included E1 (KCNMB1), E4 (KCNN3), E9 (KCNH1, KCNK15), E15 (KCNT2), E22 (KCNK5, KCNK15), E33 (KCNQ1-OT1), E38 (KCNMA1), E48 (KCNJ9), and E63 (KCNK12)." (PMID 40867621, 2025).
lung carcinoma (3 papers, 2022 to 2024). "In agreement, a lower expression of miR-202 and high expression of KCNK15 and WISP2 antisense RNA 1 (KCNK15-AS1) in fresh lung adenocarcinoma samples was associated with poor prognosis, while silencing of KCNK15-AS1 inhibited lung cancer cell proliferation via upregulation of miR-370 and miR-202." (PMID 35682549, 2022). "RP11-445H22 is a KCNK15 and WISP2 antisense RNA and it has been found as an oncogene in lung cancer and gastric cancer." (PMID 36463330, 2022).
hepatocellular carcinoma (2 papers, 2021 to 2025). A malignant tumor that arises from hepatocytes. "KCNK15 has been regarded as a potential diagnostic and prognostic biomarker of hepatocellular carcinoma." (PMID 34853296, 2021).
liver cancer (2 papers, 2019 to 2021). An epithelial or non-epithelial malignant neoplasm that arises from the liver. "We observed reduced expression of KCNK2, KCNK15, and KCNK17 in liver cancer, as well as overexpression of KCNK9, all of which correlated with a better prognosis for HCC patients per survival analyses." (PMID 31581133, 2019).
schizophrenia (2 papers, 2014 to 2023). A major psychotic disorder characterized by abnormalities in the perception or expression of reality. "In another whole-genome DNA methylation study, six genes (APIS3, C16orf59, KCNK15, LOC146336, MGC16384, and XRN2) were found to be hypermethylated and were identified as good markers of treatment-induced effects in male schizophrenia patients before and after achieving complete remission." (PMID 37772416, 2023).
Chagas disease (1 paper, 2022). A parasitic infection caused by Trypanosoma cruzi. "All those genes are involved in biological process associated to Chagas disease: nervous system (LHX6, POU6F2, MDGA1, DISC1, PCSK9), immune system (ZMIZ, HLA-DRB1), Wnt pathway (DISC1), ion transport (KCNK15, PCSK9), striated muscles (SMYD3) or ATP metabolic process (ATP5S)." (PMID 36248819, 2022).
pancreatic cancer (1 paper, 2025). "Also, KCNK15 (also known as KCNK14) was found to be upregulated in pancreatic cancer cell lines, in which it promotes proliferation and migration." (PMID 40427758, 2025).
thyroid cancer (1 paper, 2020). "This study implied that KCNK2, KCNK4, KCNK5 and KCNK15 are potential targets of precision therapy for patients with thyroid cancer and these genes are new biomarkers for the therapeutic target for thyroid cancer." (PMID 32742463, 2020). "Besides, we found that KCNK5 and KCNK15, which were highly expressed in thyroid cancer, had a better overall survival rate." (PMID 32742463, 2020). "In summary, by analyzing the differential expression of KCNKs genes, clinical staging analysis, prognosis analysis and functional enrichment analysis, we found that only four genes, KCNK2, KCNK4, KCNK5, and KCNK15, may play a role in the carcinogenesis of thyroid cancer." (PMID 32742463, 2020).
Ventricular arrhythmia (1 paper, 2019). "While KCNK17 channels expressed in human heart atrial tissue represent potential therapeutic targets to treat atrial and ventricular arrhythmias, to the best of our knowledge, our study is the first to report dysregulated expression of KCNK15 and KCNK17 mRNA and protein in HCC tissues." (PMID 31581133, 2019).
tumor (4 papers, 2017 to 2023). "KCNK6 and KCNK15 overexpression (associated in our study with luminal-A subtype) also appeared to be associated with tumor sample-type (both p < 2.2 × 10−16)." (PMID 28899398, 2017). "In pancreatic cancer, ALKBH5 plays a pro-oncogenic role and ALKBH5 overexpression can promote tumor progression by downregulating potassium two-pore domain channel subfamily K member 15 and WISP2 antisense RNA 1 (KCNK15-AS1), an oncogene, to promote tumor growth invasion and metastasis." (PMID 37063421, 2023). "Compared with tumor-adjacent tissues, KCNK5 and KCNK15 proteins were higher in PTC tissues and KCNK2 and KCNK4 proteins were lower in PTC, especially in PTC cytoplasm." (PMID 32742463, 2020). "Next, we used Western Blot to measure the protein levels of KCNK2, KCNK9, KCNK15, and KCNK17 in four pairs of HCC tissues and matched non-tumor tissues." (PMID 31581133, 2019). "To confirm our conclusions above, we used qRT-PCR to measure the mRNA levels of KCNK2, KCNK9, KCNK15, and KCNK17 in 90 pairs of HCC specimens and matched non-tumor specimens, which were surgically removed from HCC patients." (PMID 31581133, 2019). "On the other hand, mRNA levels of KCNK3, KCNK13, KCNK15, and KCNK17 correlated positively with tumor differentiation." (PMID 31581133, 2019). "Moreover, a total of 7 KCNKs were found to be closely related to the tumor stage, which were KCNK1, KCNK2, KCNK5, KCNK6, KCNK7, KCNK19, and KCNK15." (PMID 32742463, 2020).
cancer (3 papers, 2019 to 2024). A tumor composed of atypical neoplastic, often pleomorphic cells that invade other tissues. "The data show that mRNA expression of KCNK1, KCNK7, and KCNK9 is upregulated in cancer tissues while KCNK2, KCNK3, KCNK5, KCNK10, KCNK13, KCNK15, and KCNK17 levels are decreased compared to controls." (PMID 31581133, 2019).
KCNK15 also shares sentences with these, for which no sentence is quoted: atrial fibrillation (1 paper); central sleep apnea (1); diabetes mellitus (1); lung adenocarcinoma (1); papillary thyroid carcinoma (1); pulmonary arterial hypertension (1).